NUP210 (nucleoporin 210)
Diseases named in the same sentence as NUP210 in open-access papers:
NUP210 is named in the same sentence as 53 diseases in open-access papers, as found by Europe PMC text mining. Sharing a sentence is not in itself a finding about the gene and the disease. The quoted sentences say what the papers report.
primary biliary cholangitis (23 papers, 2012 to 2025). Primary biliary cholangitis (PBC) is a chronic and slowly progressive cholestatic liver disease of autoimmune etiology characterized by injury of the intrahepatic bile ducts that may eventually lead to liver failure. "The NUP210 gene has been associated with diseases, such as autoimmune disease of the urogenital tract and primary biliary cirrhosis (PBC), and PBC is related to pulmonary hypertension and polymyositis." (PMID 28924246, 2017). "Gene-specific expression studies identified Nup210 or gp210 as one of the prime targets for autoantibodies in primary biliary cholangitis (PBC), an autoimmune disease of the liver." (PMID 34970494, 2021). "The functional role of Nup210 in T cell activation identified here makes the highly specific link between anti-Nup210 autoantibodies and primary biliary cirrhosis, a T cell-mediated autoimmune disease, even more intriguing." (PMID 30323813, 2018).
breast carcinoma (5 papers, 2021 to 2025). "The expression of Nup210 has been linked to metastasis in human breast cancer patients, making it a potential metastasis susceptibility gene, particularly for ER+ breast cancers." (PMID 39459201, 2024). "Here, we identify nucleoporin NUP210 as a metastasis susceptibility gene for human estrogen receptor positive (ER+) breast cancer and a cellular mechanosensor." (PMID 34903738, 2021). "Here, we have identified Nup210 as a potential metastasis susceptibility gene for human ER+ breast cancer patients and demonstrated a previously unrecognized role of nuclear pore proteins in sensing the mechanical stress of the ECM." (PMID 34903738, 2021). "We decided to examine NUP210–histone H3.1 interaction due to the potential association of H3.1 with poor outcome in breast cancer patients (P = 0.0642) in METABRIC dataset and reported mutations of histone H3.1 in human cancer." (PMID 34903738, 2021). "Moreover, NUP210 has been defined as a metastasis susceptibility factor, since it is responsive to mechanical signals of the extracellular microenvironment and promotes lung metastasis in mouse models of breast cancer through alteration of the mechanical response, focal adhesion, and cell migration." (PMID 39858538, 2025). "Analysis of a small human breast cancer tissue microarray (TMA) revealed that the NUP210 protein level was heterogeneous among the primary tumors of both ER+ and ER− patients." (PMID 34903738, 2021). "Consistently, the protein level of phospho-FAK (Y397) was also decreased in NUP210-depleted mouse and human breast cancer cells." (PMID 34903738, 2021). "METABRIC data suggest that NUP210 expression is higher in luminal B and basal subtypes than in luminal A, Her2+, and claudin-low subtypes of breast cancer." (PMID 34903738, 2021). "Taken together, these results indicate that Nup210 promotes lung metastasis in mouse models of luminal breast cancer." (PMID 34903738, 2021). "However, the NUP210 level was significantly higher in the lymph node metastases of ER+ than ER− patients, consistent with the survival outcome of the breast cancer patient in different datasets." (PMID 34903738, 2021). "Nup210 depletion suppresses lung metastasis in mouse models of breast cancer." (PMID 34903738, 2021). "CTCF binding on Nup210 promoter also appeared to be evolutionarily conserved between mouse and human based on the analysis in MCF7 human breast cancer cell line." (PMID 34903738, 2021). "Analysis in publicly available gene expression data of breast cancer patients revealed that visceral metastases (lung, liver) have significantly higher expression of NUP210 than nonvisceral metastases (lymph node)." (PMID 34903738, 2021).
colorectal cancer (2 papers, 2022 to 2023). A primary or metastatic malignant neoplasm that affects the colon or rectum. "Regarding the mechanism involved in this, we also identified NUP210 as a BRD4-driven NUP and determinant of the nuclear architecture in colorectal cancer cells." (PMID 35159127, 2022). "We also demonstrated that the nucleoporin NUP210 was overexpressed and its expression was driven by BRD4, which regulated the proliferative ability and nuclear architecture of colorectal cancer cells." (PMID 35159127, 2022).
hepatocellular carcinoma (2 papers, 2017 to 2023). A malignant tumor that arises from hepatocytes. "It is highly upregulated in hepatocellular carcinoma (HCC), leading to the expression of Nucleoporin 210 (NUP210), important for xenobiotic metabolism." (PMID 37093326, 2023).
meningioma (2 papers, 2023 to 2025). A generally slow growing tumor attached to the dura mater. "NUP210 shows a higher expression in cervical cancer, prostate cancer, liver cancer, and meningiomas than normal tissues." (PMID 40861463, 2025). "We found that lncRNA- NUP210, lncRNA-SPIRE2, lncRNA-SLC7A1, lncRNA-DMTN, lncRNA-LINC00702, and lncRNA-LINC00460 are upregulated in meningioma cells." (PMID 36883085, 2023).
prostate carcinoma (2 papers, 2021 to 2025). A carcinoma that arises from epithelial cells of the prostate gland. "Furthermore, NUP210 expression is significantly higher in metastases than primary tumor of prostate cancer and melanoma." (PMID 34903738, 2021).
viral infection (2 papers, 2022 to 2024). "In P2–P8 (PWH on suppressive ART), 5 host genes were significantly upregulated in HIV-1 RNA–producing CSF CD4 TCM, including the nucleoporin gene NUP210, previously associated with viral infection in vitro." (PMID 38587074, 2024).
colon cancer (1 paper, 2022). "To evaluate whether NUP210 is functionally involved in colon cancer cells, we investigated the growth ability as well as nuclear morphology of HCT116 cells stably expressing shRNA targeting NUP210." (PMID 35159127, 2022). "The transcript levels of four NUPs (NUP210, NUP58, NUP37, and Rae1) were higher in colon cancer tissue among BRD4-bound NUPs." (PMID 35159127, 2022).
diabetes (1 paper, 2024). "In particular for ESKD, we have identified three genes that might help identify people with a higher risk of developing this more aggressive form of kidney disease, both in the overall population (NUP210 and SLC4A1) and in people with diabetes (SURF1)." (PMID 38858654, 2024).
endometriosis (1 paper, 2021). The growth of functional endometrial tissue in anatomic sites outside the uterine body. "Here, a genetic modification in the 3’-UTR of NUP210 gene, i.e., Rs354476 polymorphism (miRSNP or SNP at microRNA binding site), affects its binding with hsa-miR-125b-5p, a microRNA critical in the development of endometriosis." (PMID 34970494, 2021).
Hypertension (1 paper, 2017). The presence of chronic increased pressure in the systemic arterial system. "However, we are unable to corroborate a direct effect for NUP210, GAL2 and DPP6 on blood pressure and hypertension, but we suggest that these genes could be indirectly related to blood pressure and hypertension." (PMID 28924246, 2017).
kidney damage (1 paper, 2024). "We confirmed the influence of several known NEMG on kidney disease and function and found novel associations for SLC39A13, CFL1, ACP2 or ATP5G1 with serum variables and kidney damage, and for SLC4A1, NUP210 and MYH14 with ESKD." (PMID 38858654, 2024).
lung adenocarcinoma (1 paper, 2016). A carcinoma that arises from the lung and is characterized by the presence of malignant glandular epithelial cells. "We determined that NUP210 gene encoding a main component of the nuclear pore complex presented both H3K27ac and H3K4me3 histone modifications in its promoter regions among ≥85% (22 out of 26) and ≤96% (25 out of 26) of the lung adenocarcinoma cell lines." (PMID 27042856, 2016). "The results indicate that NUP210 gene is the most promising epigenetic biomarker for lung adenocarcinoma." (PMID 27042856, 2016). "Frequency of lung adenocarcinoma tissue samples showing aberrant NUP210 expression was about 19.3% and that of the other 10 types of carcinoma was 0–17.7%." (PMID 27042856, 2016). "The number of lung adenocarcinoma cell lines aberrantly expressing NUP210, PKN1, and PPP1R9A was 26, 26, and 8, respectively." (PMID 27042856, 2016). "RNA-Seq analysis revealed that NUP210 was aberrantly overexpressed among the 26 lung adenocarcinoma cell lines, although the frequency of NUP210 overexpression was lower (19.3%) in 57 lung adenocarcinoma tissue samples studied and stored in another database." (PMID 27042856, 2016). "It is worth noting that NUP210 and PKN1 genes were aberrantly expressed in all of the 26 lung adenocarcinoma cells." (PMID 27042856, 2016). "For example, the FPKM value of NUP210 in each of the lung adenocarcinoma tissue sample and the normal lung tissue sample is shown in S9 Table, together with the levels in RPKM seen in the cell line data." (PMID 27042856, 2016). "Thus, we investigated the expression levels (in RPKM) of the three genes (NUP210, PKN1, and PPP1R9A) in each of the lung adenocarcinoma cell lines and compared it with that in SAEC." (PMID 27042856, 2016). "In order to increase its reliability as a biomarker, further studies are warranted to systematically investigate the presence or absence of the dual histone modification in the promoter of NUP210 among other lung adenocarcinoma cells and normal cells." (PMID 27042856, 2016).
metastatic prostate carcinoma (1 paper, 2025). A carcinoma that arises from the prostate gland and has spread to other anatomic sites. "In addition, elevated levels of other NUPs downregulated by bromoxib in TPP (i.e., NUP188, NUP210, NUP85, NUP62, and NUP214) were identified in metastatic prostate cancer, suggesting that NPC dysregulation may drive aggressive cancer phenotypes." (PMID 40137294, 2025).
Obesity (1 paper, 2020). Accumulation of substantial excess body fat. "These genes were also examined in female placentae, however, only Pi15, Nup210, Acta2, Rnf222, and Muc15 were significantly modulated by obesity." (PMID 32203108, 2020).
cancer (10 papers, 2016 to 2025). A tumor composed of atypical neoplastic, often pleomorphic cells that invade other tissues. "When we analysed the cancer-specific genes like Cdc20, Hmmr, Tpx2, Cenpf, Birc5, Ube2c, Foxm1,Pold4, Nup210, Cenpm and Orc1, these pro-carcinogenic genes found to be over expressed in the disease control group." (PMID 36650455, 2023). "Together, our results suggest that BRD4-driven NUP210 regulates cancer cell growth and nuclear architecture." (PMID 35159127, 2022). "In conclusion, we have identified a previously unrecognized role for nuclear pore protein, NUP210, in mechanical sensing of aggressive metastatic cancer cells." (PMID 34903738, 2021). "NUP210 is a nucleoporin whose primary function is the formation of pores to regulate the exchange between nucleoplasm and cytoplasm; however, it has been recently demonstrated to have a role in cancer." (PMID 39858538, 2025). "A high expression of SDHA and NUP210 were positively associated with the unfavorable prognosis of AML patients and an elevated expression of SLC27A4 was linked to poorer clinical outcomes in several cancer types." (PMID 38254953, 2023). "NUP210 mediates muscle cell differentiation by regulating nuclear envelope (NE) endoplasmic reticulum homeostasis and a recent study of NE proteins in cancer samples revealed that NUP210 is usually upregulated in tumors (particularly in ovary, breast, and prostate)." (PMID 27042856, 2016). "Whether NUP210 may also serve an anti-apoptotic function in cancer cells is currently unknown." (PMID 32545200, 2020). "By focusing on the three genes above (NUP210, PKN1, and PPP1R9A), we examined their functions and known relationships with cancer." (PMID 27042856, 2016). "The function of NUP210 in cancer is not clear; however, a study demonstrated that AR–V7 promotes the proliferation of CRPC cells in a NUP210-dependent manner." (PMID 37686409, 2023). "Among the top 100 gene elements on this axis, we selected 10 candidates, including RAB39A, CPVL, NUP210 and LHX2, which were robustly expressed in cancer cells and CSCs but not in normal MSCs or Fb in both acidic and neutral environments." (PMID 29515775, 2018).
tumor (7 papers, 2011 to 2025). "Similar to short hairpin RNA (shRNA) result, Nup210 KO in two different clones, N9 and N13, diminished primary tumor weight and lung metastases." (PMID 34903738, 2021). "Many of the deregulated transcripts identified in U-E6All cells have been previously identified in HPV-infected cells and tumor samples such as transcripts encoding ribosomal subunits, SYCP2, NUP210 and DICER129–33." (PMID 30976051, 2019). "Alongside RGPD genes, NUP210—another nuclear pore complex component—plays a critical role in facilitating metastatic potential by maintaining nuclear pore integrity, modulating chromatin architecture, and enabling tumor cells to respond to mechanical stress." (PMID 40370715, 2025). "In addition, all EpiTCer bead/DC ratios induced a higher frequency of CD107a+ CD8+ T cells compared to more traditional ways to pulse DC with antigens, such as custom made 9mer neoantigen peptides, ETV6 and NUP210, or whole tumor lysate." (PMID 35433456, 2022). "After 14 days of stimulating CD8+ T cells with antigen-loaded DC, tumor reactivity was analyzed by re-stimulation of CD8+ T cells with ANRU tumor cells or with the ETV6/NUP210 9mer neoantigen peptides (only for T cell that had been co-cultured with DC pulsed with the corresponding 9mer peptide)." (PMID 35433456, 2022). "Next, we assessed if loading the DC with pooled ETV6 and NUP210 peptides could increase the enrichment for tumor-specific T cells to a similar extent as the one observed with EpiTCer-beads-loaded DC." (PMID 35433456, 2022). "However, DC loaded with either neoantigen 9mer peptides, ETV6 or NUP210, or tumor lysate induced increased frequencies of tumor reactive CD8+ T cells when compared to the unloaded DC, MOCK." (PMID 35433456, 2022). "Primary tumors derived from orthotopically implanted Nup210 short hairpin RNA knockdown cells showed variability in tumor weight, with decreased tumor weight for 4T1 cells, but increased tumor weights for both 6DT1 and MVT1 cells." (PMID 34903738, 2021). "As focal adhesion contributes to the mechanical response of tumor cells, we asked whether NUP210 is mechanosensitive in metastatic cells." (PMID 34903738, 2021). "However, three glycolysis-related genes (ADH1B, ADH5, and NUP210) were significantly differentially expressed at the mRNA level in tumor tissues versus adjacent normal tissues but were not significantly related to patient prognosis (p > 0.05)." (PMID 34595101, 2021). "In addition, and in contrast to both the MS results and the results with the dextramer-sorted cells, in this experiment, NUP210-dextramer-positive cells recognized the tumor demonstrated by tumor-induced activation of degranulation." (PMID 31921104, 2019). "All three healthy donors' CD8+ T cells stimulated either with DC pulsed with the NUP210 or the MART-1 epitope could also recognize the ANRU tumor." (PMID 31921104, 2019). "However, Nup210 knockdown resulted in a decrease in pulmonary metastases for all three cell lines, and this decrease was preserved after normalizing metastasis counts by tumor weight to account for the variability in primary tumor growth." (PMID 34903738, 2021). "ANRU imDC were loaded with tumor lysate, ETV6 or NUP210 9mer peptides, or several ratios of EpiTCer beads." (PMID 35433456, 2022). "In both healthy donors, EpiTCer-loaded DC induced an increased frequency of CD8+ tumor-specific T cells compared to ETV6 and NUP210 peptides delivered separately or in pools." (PMID 35433456, 2022). "Taken together, these results demonstrate that NUP210 is part of a sensor of the extracellular matrix (ECM) stiffness and composition that significantly affects the migratory and invasive ability of tumor cells." (PMID 34903738, 2021). "In contrast, CTC counts in mice with Nup210-depleted tumors were indistinguishable from the FVB tumor-free control." (PMID 34903738, 2021).
tumor (continued). "IFN-γ-treated tumor cells were also recognized by TIL specific for the neoepitope NUP210, but the activation only resulted in degranulation, not in IFN-γ production." (PMID 31921104, 2019). "UBE2C, CCNB1, CCNB2, PLOD2, NUP210, MELK, CDC20 were overexpressed in tumours and in CIN3/CIS relative to both Normal and CIN1/CIN2, suggesting that they could have an important role to play in the early phase of tumorigenesis." (PMID 21338529, 2011). "UBE2C, CCNB1, CCNB2, PLOD2, NUP210, MELK, CDC20 genes were overexpressed in tumours and in CIN3/CIS relative to both Normal and CIN1/CIN2, suggesting that they could have a role to play in the early phase of tumorigenesis." (PMID 21338529, 2011). "Notably, there was no additive effect on tumor recognition when stimulating CD8+ T cells with DC loaded with ETV6 combined with NUP210." (PMID 35433456, 2022).
NUP210 also shares sentences with these, for which no sentence is quoted: cholestasis (7 papers); Cirrhosis (7); Hepatic failure (7); autoimmune hepatitis (5); Liver Diseases (5); overlap syndrome (4); autoimmune disease (3); infection (3); Hepatic fibrosis (2); liver cirrhosis (2); osteosarcoma (2); portal hypertension (2); primary Sjögren's syndrome (2); acute liver failure (1); amyotrophic lateral sclerosis (1); autoimmune hemolytic anemia (1); Autoimmunity (1); bacterial infection (1); brain tumours (1); cervical cancer (1); cholangitis (1); co-infection (1); fibrosis (1); gastric cancer (1); head and neck cancer (1); Immunodeficiency (1); Jaundice (1); kidney disease (1); liver cancer (1); melanoma (1).
A further 6 diseases each share a sentence with NUP210 in 1 paper.